GIMAP3P (GTPase, IMAP family member 3 pseudogene)
Synonyms: GIMAP3; IAN4P
Gene: Processed pseudogene on chromosome 7 (150,746,893 to 150,747,728, reverse strand). Ensembl gene ENSG00000177590.
Diseases named in the same sentence as GIMAP3P in open-access papers:
GIMAP3P is named in the same sentence as 3 diseases in open-access papers, as found by Europe PMC text mining. Sharing a sentence is not in itself a finding about the gene and the disease.
GIMAP3P shares sentences with these, for which no sentence is quoted: lung carcinoma (1 paper); lymphopenia (1); mitochondrial disease (1).